ABCC12 (ATP binding cassette subfamily C member 12)
Description:
Probable transporter, its substrate specificity is unknown.
Synonyms: MRP9
Tractability: Small molecule: it belongs to a druggable protein family. Antibody: UniProt predicts a signal peptide or a membrane-spanning region. PROTAC: ubiquitination databases record sites on it.
Gene: Protein-coding gene on chromosome 16 (48,080,882 to 48,156,018, reverse strand). Ensembl gene ENSG00000140798.
Subcellular location: Endoplasmic reticulum membrane
Gene Ontology:
Molecular function: ABC-type transporter activity; ATP binding; ATP hydrolysis activity
Biological process: transmembrane transport
Cellular component: endoplasmic reticulum; membrane; endoplasmic reticulum membrane
Genetic constraint (gnomAD): Loss-of-function variants: 139 observed, 156.58 expected, observed/expected ratio (o/e) 0.89, 90% interval 0.77 to 1.02. The upper end of that interval is the gene's LOEUF score, 1.02, which puts it in group 4 of 6, group 1 being the genes least tolerant of losing a copy. Missense variants: 1,628 observed, 1,767.1 expected, observed/expected ratio (o/e) 0.92, 90% interval 0.88 to 0.96. Synonymous variants: 643 observed, 677.08 expected, observed/expected ratio (o/e) 0.95, 90% interval 0.89 to 1.01.
Homologues: Orthologues: chimpanzee ABCC12 (99% identical), macaque ABCC12 (97% identical), dog ABCC12 (89% identical), pig ABCC12 (88% identical), guinea pig ABCC12 (86% identical), mouse Abcc12 (85% identical), rat Abcc12 (84% identical), rabbit ABCC12 (80% identical), zebrafish abcc12 (51% identical), Drosophila melanogaster MRP (33% identical), Drosophila melanogaster Mrp5 (29% identical), Drosophila melanogaster Mrp4 (28% identical), and 8 more. Paralogues in human: ABCC11 (47% identical), ABCC5 (44% identical), ABCC1 (32% identical), ABCC4 (31% identical), ABCC2 (31% identical), ABCC3 (31% identical), ABCC10 (29% identical), ABCC6 (29% identical), ABCC8 (27% identical), ABCC9 (27% identical), CFTR (25% identical).
Diseases named in the same sentence as ABCC12 in open-access papers:
ABCC12 is named in the same sentence as 25 diseases in open-access papers, as found by Europe PMC text mining. Sharing a sentence is not in itself a finding about the gene and the disease. The quoted sentences say what the papers report.
breast carcinoma (5 papers, 2006 to 2024). "Variations in ABCC12 are linked to breast cancer, liver hepatocellular carcinoma, bile duct paucity, cholestatic liver disease, and may also affect spermatid development and sperm function." (PMID 39238930, 2024). "The addition of MRP7 (ABCC10 gene) to the MRP subfamily was reported in 2001, to which was also later added MRP8 (ABCC11 gene) and MRP9 (ABCC12 gene); these last two are greatly expressed in breast cancer." (PMID 37092502, 2023).
breast tumor (2 papers, 2006 to 2024). "The capability of STGIC is validated indirectly by expression of marker genes of invasive breast tumor in the predicted spatial domains, which are C6orf141, PDE5A, LINC00645, BMERB1, ABCC11, ABCC12." (PMID 38416785, 2024).
ovarian carcinoma (1 paper, 2022). A malignant neoplasm originating from the surface ovarian epithelium. "For ovarian cancer, we found a borderline significant association between ABCC12 expression and overall survival for grade 3 tumors (logrank P = 0.048; HR, 1.36; CI 1 to 1.85); however, this association was lost when all cancer grades were considered (logrank P = 0.16)." (PMID 35715537, 2022).
type 2 diabetes (1 paper, 2017). "Allele Counts by type 2 diabetes status for variants in the MUC5B and ABCC12 genes." (PMID 28346466, 2017).
cancer (7 papers, 2013 to 2024). A tumor composed of atypical neoplastic, often pleomorphic cells that invade other tissues. "ABCC12 (ATP-binding cassette subfamily C member 12) is a membrane transporter of which expression is increased in cancer to confer multidrug resistance." (PMID 32947888, 2020). "The regulation of ABCC12 by CAP gives us a hint that CAP may affect cancer cells by modulating membrane transporters involved in drug delivery." (PMID 32947888, 2020).
tumor (7 papers, 2020 to 2024). "Differentially expressed genes (DEGs) between domain 4 and domain 13 includes ABCC11, ABCC12 and TFF1, in which the first two are multidrug resistance genes and the last one is associated with tumour differentiation." (PMID 36250636, 2022). "ABCC11 and ABCC12 were highly expressed in miR-18a/low tumours of the METABRIC dataset." (PMID 38786043, 2024). "Since ABCC subfamily members are thought to confer multidrug resistance to tumor cells, ABCC12 may affect pomalidomide sensitivity by controlling the efflux of pomalidomide." (PMID 32132601, 2020). "The three proteins, CTLA4, REG4, and ABCC12, which were regulated by both CAP and H2O2 have been known to be involved in tumor cell growth or drug resistance." (PMID 32947888, 2020).
ABCC12 also shares sentences with these, for which no sentence is quoted: age (1 paper); Cholestatic liver disease (1); chronic fatigue syndrome (1); colon cancer (1); cutaneous T-cell lymphoma (1); epilepsy (1); episodic kinesigenic dyskinesia 1 (1); familial cold autoinflammatory syndrome 1 (1); generalized epilepsy (1); hepatocellular carcinoma (1); lung carcinoma (1); male infertility (1); mucinous neoplasm (1); panic disorder (1); personality disorder (1); Pseudoxanthoma elasticum (1); rectal cancer (1); renal carcinoma (1); Sezary syndrome (1).